HK2 (hexokinase 2)
Diseases named in the same sentence as HK2 in open-access papers (continued):
Sharing a sentence is not in itself a finding about the gene and the disease.
glioma (continued). "Consistent with previous study, our results showed that the levels of HK2 were elevated in glioma tissues from patients with high-grade gliomas." (PMID 33922649, 2021). "The levels of miR-542-3p and HK2 were significantly elevated in glioma tissues of patients with high-grade gliomas compared to those with low-grade gliomas." (PMID 33922649, 2021). "Next, we investigated the correlation between the levels of the HK2 gene and miR-542-3p levels in patient with gliomas." (PMID 33922649, 2021). "The intensity of HK2-positive staining was elevated in tumor tissues of patients with high-grade gliomas (G3 and G4) relative to that in patients with low-grade gliomas (G1 and G2)." (PMID 33922649, 2021). "Our findings suggest that miR-542-3p regulates the high glycolytic phenotype via HK2-mediated glycolysis in gliomas." (PMID 33922649, 2021). "Our results suggest that miR-542-3p contributes to the HK2-mediated high glycolytic phenotype in human glioma cells." (PMID 33922649, 2021). "The levels of miR-542-3p and HK2 were significantly elevated in glioma tissues of patients with high-grade gliomas relative to that in low-grade gliomas." (PMID 33922649, 2021). "In this study, actinomycin D was found to significantly downregulate the expression levels of several glioma metabolic enzymes, including HK2 and PKM2 from glycolysis, GLS from glutaminolysis and FASN from lipogenesis." (PMID 34063013, 2021). "The elevation of HK2 levels in patients with high-grade gliomas were positively correlated with the high levels of miR-542-3p in GBM and low-grade gliomas (LGG) based on the datasets from the Cancer Genome Atlas (TCGA) database." (PMID 33922649, 2021). "Consistently, over-expression of miR-542-3p increased HK2-induced glycolytic activity in human glioma cells." (PMID 33922649, 2021). "Consistent with previous studies, we showed that miR-542-3p promotes the expression of HK2 and HK2-dependent high glycolytic activity in human glioma cells." (PMID 33922649, 2021). "The elevation of HK2 increased the glycolytic activity in response to glucose in human glioma cells." (PMID 33922649, 2021). "Our results suggest that high levels of HK2 are important for the high glycolytic phenotype of glioma cells in high-grade glioma." (PMID 33922649, 2021). "It has been reported that Nrf2 transcriptionally activates XO in glioma cells, which is dependent on Nrf2 and HK2 trafficking to the nucleus." (PMID 33080936, 2020). "By detecting glucose consumption, lactate production and HK2 protein level, we were the first to provide that circNFIX knockdown decreased glycolysis in glioma." (PMID 31888753, 2019). "Before and after radiotherapy significant differences were described in metabolites, cells rapidly turn to OXPHOS inhibiting mTOR and HK2 in glioma cell line, as a model system." (PMID 30574020, 2018). "Our previously established fact that Bmi1 is a direct functional target of miR-218 in glioma condition validates the miR-218 induced HK2 suppression." (PMID 29220380, 2017). "Further, the shRNA-targeted reduction of HK2 expression in glioma cell lines decreased their proliferative, invasive and migrating abilities." (PMID 29220380, 2017). "In the present study, we studied the tumorigenic role of HK2 in glioma, and clarified the mechanism of miR-218 induced HK2 regulation in glioma development." (PMID 29220380, 2017). "In the present study, it was also shown that the inhibition of HK2 resulted in a reduction of proliferation, migration and invasion of glioma cells, an effect that resembled the effect of miR-218 overexpression." (PMID 29220380, 2017). "Further, amongst the glioma samples, HK2 expression increased significantly with the progression in tumor grade, thus establishing a positive correlation." (PMID 29220380, 2017).
glioma (continued). "In response to increased expression of miR-218 in glioma cells, the gene chip microarray analysis revealed a decrease in their HK2 expression, which was further identified as a target of miR-218 by Target Scan." (PMID 29220380, 2017). "Consistent with previous reports, the results of our study reveal an increase in the HK2 expression in glioma condition, as confirmed through glioma cell lines and human glioma tissue analysis." (PMID 29220380, 2017). "Taken together, our findings confirmed the tumorigenic activity of HK2 in glioma, and the involvement of the miR218/Bmi1 pathway in the regulation of its expression." (PMID 29220380, 2017). "Despite these limitations, this study supports/demonstrates the tumorigenic activity of HK2 in glioma condition, while also establishes a novel miR-218/Bmi1/HK2 axis in regulating the same." (PMID 29220380, 2017). "In glioma the metabolic effects of ROS involve DNA damage responses and the Jnk pathway which modulates glucose uptake, ATP levels and hexokinase-2 and pyruvate kinase activity." (PMID 28491867, 2017). "The glycolytic enzyme hexokinase 2 (HK2) is crucial for the Warburg effect in human glioma, the most common malignant brain tumor." (PMID 29220380, 2017). "In accordance with our expectation, knockdown of Bmi1 expression in glioma cells dramatically decreased their expression of both HK2 mRNA and protein level." (PMID 29220380, 2017). "This indicates that the miR-218/HK2 axis, in addition to regulating glucose metabolism, plays an important role in controlling tumorigenesis in glioma, thus adding a novel molecular link between tumor biology and tumor metabolism." (PMID 29220380, 2017). "Whilst damage activates antioxidative defense by activating the PPP in glioma, Jnk activation downregulates hexokinase-2 and PKM2 obstructing glycolysis, forcing reliance on oxidative phosphorylation and sensitizing glioma cells to oxidative stress." (PMID 28491867, 2017). "The HK2 expression was significantly increased in glioma tissues comparing with the non neoplastic brain tissues and was positively correlated with the glioma grade." (PMID 29220380, 2017). "The HK2 expression in (a) lentivirus-infected, miR-218 overexpressing and (b) shRNA mediated Bmi1 silenced U87 and U251 glioma cell lines were quantified." (PMID 29220380, 2017). "Previous study showed that HK2 was induced by metabolic stress in glioma cells, furthermore, the binding of HK2 to mitochondria outer membrane, which was essential for glioma cell glycolysis, relied on PI3K-AKT pathway." (PMID 25761777, 2015). "HK2 is the first key enzyme for glycolysis and is abundantly expressed in gliomas, moreover, HK2's expression level is negatively correlated with glioma (WHO grade IV) patients' prognosis." (PMID 25761777, 2015). "In this paper, we also demonstrated that PERK silencing really blocked p-AKT and subsequently inhibited HK2's mitochondrial translocation and cell viability in glioma cells under low glucose stress." (PMID 25761777, 2015). "Overexpression of HK2 could significantly restore mitochondrial function and glucose uptake ability of Gomisin J treated glioma cells." (PMID 39991762, 2025). "HK2 depletion suppressed glycolysis and led to energy impairment in mice glioma cells." (PMID 40559415, 2025). "Similarly, silencing XBP1 reduces glioma cell viability by inhibiting HK2 expression, thereby regulating glycolysis." (PMID 39273011, 2024). "Thus, Chr-A prevented the utilization of glucose by glioma cells through the inhibition of HK2 and G6PD." (PMID 39330272, 2024). "Moreover, siRNA‐mediated knockdown of HK2 expression reversed L1‐enhanced tube formation and tumor invasion in different glioma cell lines." (PMID 36708044, 2023). "The results demonstrated that HK2 expression was increased in L1‐overexpressing glioma cells." (PMID 36708044, 2023).
glioma (continued). "Moreover, we identified that activation of the downstream PI3K/AKT signaling pathway of the L1CAM/HK2 cascade is critical for VM formation by glioma cells." (PMID 36708044, 2023). "To gain further insight into the regulatory mechanism of L1‐mediated VM formation by glioma cells, we attempted to confirm whether the activation of AKT signaling was impaired after inhibition of the L1/HK2 cascade in glioma cells." (PMID 36708044, 2023). "As we speculated, the enhancement of glioma invasion and VM formation induced by the inhibition of miR‐143‐3p could be significantly reversed after downregulation of HK2 expression in U87, T98, and GBM1 glioma cell lines." (PMID 36708044, 2023). "In addition, prognostic analyses indicated that only HK2 expression was positively correlated with poor prognosis and malignancy in glioma patients in the GEPIA and UCSC Xena databases, respectively." (PMID 36708044, 2023). "Notably, the intensity of COL5A1-positive staining and the number of cells showing subcellular co-localization of COL5A1 and NOX2 or HK2 were significantly elevated in in patients with GBM (G4) relative to that in patients with G3 glioma (G3)." (PMID 35158782, 2022). "NOX2 induces hexokinase 2 (HK2)-dependent high glycolytic activity in U87MG glioma cells." (PMID 35158782, 2022). "We expected that HK2 may regulate innate immune cells and abnormally activate the immune response, resulting in the poor prognosis of gliomas." (PMID 35982398, 2022). "With the higher histological grade of glioma, the mRNA expression of HK2 tended to be higher." (PMID 35982398, 2022). "Furthermore, ROC curves of four prognostic models, including OS, PFS, DSS, and DFS, revealed that high expression of HK2 was positively correlated with poor prognosis in glioma." (PMID 35982398, 2022). "In addition, the GEPIA database also showed correlations between the individual expression of these hub genes and HK2, suggesting that HK2 is probably involved in glioma development by regulating its hub genes." (PMID 35982398, 2022). "Due to the potential roles of HK2 in glioma development, we hypothesized that HK2 might represent a new target for the treatment of glioma." (PMID 35982398, 2022). "Moreover, the levels of the HK2 gene were significantly elevated in GBM (G4) compared to G2 glioma (G2) in the analysis of the GBM and LGG datasets from TCGA and REMBRANDT." (PMID 35158782, 2022). "In addition, we performed univariate, multivariate Cox regression and nomogram analyses of the hub genes positively and negatively correlated with HK2 to explore the potential regulatory mechanism in the initiation and development of glioma." (PMID 35982398, 2022). "In summary, integrated bioinformatics approaches indicated that HK2 expression may mediate immune infiltration to affect the prognosis of glioma patients and may be a potential prognostic biomarker." (PMID 35982398, 2022). "Next, we subjected glioma TMA for immunostaining by applying anti-HK2 antibody." (PMID 35982398, 2022). "Since the aberrant HK2 expression was critical for glioma development in vivo and in vitro, we next examined whether the inhibition of HK2 could suppress tumour development in glioma cells." (PMID 35982398, 2022). "Therefore, we attempted to establish HK2-knockdown glioma cell lines through respectively transfecting two siRNAs targeted to HK2 in T98 and GBM1 cells." (PMID 35982398, 2022). "Together, our findings suggested that HK2 expression might be a potential biomarker for predicting prognosis of the patients with glioma." (PMID 35982398, 2022). "In this study, we investigated the potential roles of HK2 expression in predicting prognosis on the basis of various databases and explored the correlation with clinicopathological features and the possible regulatory mechanism in glioma." (PMID 35982398, 2022).
glioma (continued). "In addition, we also found that the VM Formation was also inhibited after inhibiting HK2 expression in glioma cells, suggesting that the HK2 is potentially related to tumorigenesis and tumour development in the patients with glioma." (PMID 35982398, 2022). "Several reports have demonstrated that highly expressed HKs (mostly of the HK2 isoform) are positively correlated with tumorigenesis in many malignant tumours, including glioma, bladder cancer, oral squamous cell carcinoma, colorectal cancer, and breast cancer." (PMID 35982398, 2022). "In addition, HK2 expression was significantly correlated with clinical parameters, histological manifestations, and prognosis in glioma patients." (PMID 35982398, 2022). "In addition, HK2 and its hub genes mediate the activation of immune cells and the regulation of immune-related factors and are involved in the prognosis of glioma patients." (PMID 35982398, 2022). "We first analyzed the protein levels of HK2 in patients with low- and high-grade gliomas." (PMID 33922649, 2021). "Knockdown of miR-542-3p suppressed HK2-induced glycolytic activity in human glioma cells." (PMID 33922649, 2021). "However, the mechanism for the regulation of the HK2-dependent high glycolytic phenotype in high-grade glioma is still unclear." (PMID 33922649, 2021). "Based on these previous studies, STAT3 or miR-143a might be a molecular target in the regulation of HK2 expression in human glioma cells." (PMID 33922649, 2021). "Conclusively, our findings suggest that miR-542-3p might be a critical molecule for the HK2-mediated high glycolytic phenotype in glioma." (PMID 33922649, 2021). "In contrast to the level of HK2 in normal brains and low-grade gliomas, HK2 expression is increased in GBM tumours and is correlated with worse overall survival in patients with this disease.Recently, deregulated HK2 expression was also found to play a role in the pathogenesis of OSCC." (PMID 27926482, 2017). "Considering our previously established miR-218/Bmi1 pathway in glioma inhibition, we hypothesized that Bmi1 may fill the gap between miR-218 induced HK2 suppression." (PMID 29220380, 2017). "Indeed, it was observed that overexpression of miR-218 in glioma tumor cells did obviously decrease HK2 mRNA and protein expression, though luciferase activity analysis declined HK2 as a direct target of miR-218." (PMID 29220380, 2017). "In conclusion, downregulation of HK2 expression via shRNA led to the inhibition of glioma." (PMID 29220380, 2017). "The tumorigenic role of HK2 in glioma cells was assessed in vivo, using nude mice." (PMID 29220380, 2017). "Although these results were contrary to our expectation, further supported that miR-218 might regulate glioma cells development by regulating many genes besides HK2." (PMID 29220380, 2017). "The HK2 expression in patient derived glioma and non neoplastic brain tissue was quantified." (PMID 29220380, 2017). "Sensitization to radiation following HK2 loss may be due to downstream disruption of ERK 1/2 signaling, which has been shown to promote radio-resistance in glioma." (PMID 27588472, 2016). "Whether PERK phosphorylation under the microenviromental stress in glioma tissues may stimulate glycolysis via the regulation of AKT pathway on HK2 remains unclear." (PMID 25761777, 2015). "Therefore, this L1/HK2 cascade can be considered a potential clinical target for reducing VM formation to improve the therapeutic benefit of antiangiogenic treatment for patients with glioma." (PMID 36708044, 2023). "In addition, western blot analysis showed that HK2 expression was significantly upregulated in in‐miR‐143‐3p‐treated U87, T98, and GBM1 glioma cells, implying that miR‐143‐3p could regulate HK2 expression by targeting the 3'UTR of the HK2 gene in glioma." (PMID 36708044, 2023).
glioma (continued). "Therefore, our findings demonstrated that HK2 and its hub genes are significantly correlated with prognosis and immune infiltration in glioma and may be potential targets for the treatment of patients with glioma." (PMID 35982398, 2022). "Moreover, we correlated HK2 expression with clinicopathologic characteristics of glioma." (PMID 35982398, 2022). "Therefore, our findings suggested that HK2 might be a potential biomarker for investigating glioma development and predicting prognosis in glioma patients." (PMID 35982398, 2022). "We next investigated whether miR-542-3p could regulate the levels of HK2 in patients with gliomas." (PMID 33922649, 2021). "Moreover, the levels of miR-542-3p and HK2 are elevated in patients with gliomas." (PMID 33922649, 2021). "To address our hypothesis, we performed glucose uptake assays and found that SNHG1 downregulation suppressed glucose uptake in glioma cells and attenuated the expression of genes involved in glucose metabolism, including HK2 and GLUT1 (, whereas the upregulation of SNHG1 showed the opposite results." (PMID 31189920, 2019). "In addition to its critical metabolic role, HK2 could also promote glioma survival, against chemo or radiation insult, by repressing mitochondria mediated apoptotic pathway in glioma cells." (PMID 29220380, 2017). "The increased expression of HK2, PFKM, SLC2A1, and PKM2 induced by TGF-β has been observed in several types of cancer, including gliomas, particularly under hypoxic conditions." (PMID 40943648, 2025). "Hexokinase 2 (HK2) is the initial rate-limiting enzyme in the glycolytic pathway, and its abnormal expression in gliomas promotes malignant progression." (PMID 39272133, 2024). "Meanwhile, we checked the expression of CAV1 with the key glycolysis pathway genes HK2 and GLUT3(SLC2A3) in gliomas and found that the expression of CAV1 is positively related to HK2 and GLUT3." (PMID 37642765, 2023). "Analyses of quantitative real-time PCR confirmed that S/G deprivation significantly induced the mRNA expression levels of GLUT1, GLUT 3, HK2, and PFKFB2 in glioma stem cells (GSCs) and GBM cells, including U87MG, LN18, and A172." (PMID 38098117, 2023). "The expression of enolase 1 (ENO1) and hexokinase 2 (HK2) has been shown to play an important role in the occurrence and metastasis of glioma cells." (PMID 37627013, 2023). "For example, Gomisin J, a derivate of lignan, reduces the expression of HK2 and disrupts the bond between HK2 and VDAC, leading to apoptosis and tumor reduction in glioma." (PMID 38139462, 2023). "In contrast, the blockade of the miR‐143‐3p/HK2 cascade would potently disrupt neurosphere formation, and downregulate CD133 expression, to reverse L1‐enhanced glioma stem cell growth." (PMID 36708044, 2023). "Thus, HK2 and its hub genes may be a potential target for the treatment of glioma." (PMID 35982398, 2022). "The expression levels of HK2 and NOX2 mRNA were positively correlated in patients with glioma in the analysis of the GBM and LGG datasets from TCGA." (PMID 35158782, 2022). "Similar to the cohort I, the levels of HK2 and NOX2 were elevated in patients with G3 glioma (G3) relative to those in G1 and G2 gliomas (G1, G2) in the cohort II." (PMID 35158782, 2022). "In glioma cells, silencing XBP1 suppresses hexokinase-2 (HK2) therefore inhibiting glycolysis and resulting in cell death." (PMID 35346303, 2022). "Histological measurements revealed higher expression of HIF1a, GLUT3, and HK2 in labels in category W than in category M, which corresponded with the comparison between IDH wild-type and mutant gliomas based on pathological diagnoses." (PMID 35058510, 2022). "Previous research demonstrated that long noncoding RNA 01060 (lncRNA01060) increases MZF1 translocation into the nucleus and promotes MZF1-regulated c-Myc, HK2, and PGK1 transcription in glioma, facilitating aerobic glycolysis and inducing tumor progression." (PMID 36499054, 2022).